ALB (albumin)
Diseases named in the same sentence as ALB in open-access papers (continued):
Sharing a sentence is not in itself a finding about the gene and the disease.
Sepsis (continued). "Clinical trials, despite supporting the safety of HSA administration, failed to provide sufficient evidence in favor of the use of albumin as the resuscitation fluid of choice for patients with severe sepsis and septic shock." (PMID 26942605, 2016). "Second, sepsis is often associated with marked reduction in corticosteroid-binding globulin (CBG) and albumin." (PMID 27379022, 2016). "A single plasma albumin measurement on the bacteraemia date was a better prognostic predictor of short-term mortality than the sepsis severity score." (PMID 27611431, 2016). "Protein metabolism is significantly disturbed after any kind of traumatic event, for example, surgery, sepsis, and burn injuries; albumin has been identified as a reliable indicator of this process." (PMID 26880899, 2016). "Sepsis patients had lower albumin concentrations and higher SHBG concentrations than control subjects." (PMID 27765072, 2016). "Between albumin values and duration of hospital stay (r = −0.298), mortality (r = −0.355), pulmonary complications (r = −0.257), sepsis (r = −0.191), and inotropic use (r = −0.246), there was a negative correlation (P < 0.05)." (PMID 27749567, 2016). "The magnitude of observed differences is comparable to those reported for albumin leak in other experimental models of sepsis." (PMID 25959381, 2015). "In conclusion, the CRP/albumin ratio is an independent predictor of long-term mortality in patients with severe sepsis or septic shock." (PMID 26158725, 2015). "Increased microvascular permeability due to a breakdown of the endothelial glycocalix results in an increased transcapillary escape rate of albumin in experimental sepsis." (PMID 26232247, 2015). "In sepsis, inflammatory injury to the glycocalyx increases porosity of endothelium, and albumin can flow through the ETCs; πiv increases and this further opposes back-filtration of fluid and drives edema formation." (PMID 25887223, 2015). "Nevertheless, the current researches mainly focus on using albumin as one kind of colloids for fluid resuscitation in patients with severe sepsis and septic shock." (PMID 26557421, 2015). "In the present study, CLP-induced sepsis resulted in increased levels of albumin in BAL, W/D ratio and extravasated EBA in lung tissue as well as revealed an increase in pulmonary vascular permeability." (PMID 25405912, 2015). "Western blot analysis of proteins extracted from fragments of the lung, kidney, and liver showed higher tissue albumin levels (normalized to β-actin) in ALI-sepsis mice compared with controls." (PMID 25959381, 2015). "Secondly, albumin is another kind of colloids being considered to infuse during the early resuscitation of patients with severe sepsis." (PMID 26273142, 2015). "Compared to sham mice, CLP-sepsis resulted in pulmonary microvascular barrier dysfunction, quantified by increased EB-albumin leak, and PMVEC death (PI+ staining) as early as 2 h and more marked by 4 h after CLP." (PMID 26376777, 2015). "Our study shows that the CRP/albumin ratio at admission can be used as an independent predictor of 180-day mortality in patients with severe sepsis or septic shock." (PMID 26158725, 2015). "The CRP/albumin ratio was an independent predictor of mortality in patients with severe sepsis or septic shock." (PMID 26158725, 2015). "The ROC curves were also performed to assess the levels of albumin on predicting the prognosis of sepsis." (PMID 26557421, 2015). "In this study, the CRP/albumin ratio at admission was positively correlated with the prognosis in severe sepsis and septic shock patients treated with EGDT." (PMID 26158725, 2015). "It has been noted that sepsis can increase the risk of severe hyperbilirubinaemia and or bilirubin neurotoxicity by altering the binding affinity of albumin, and that sepsis can result in acute, severe hyperbilirubinaemia." (PMID 27057339, 2015).
Sepsis (continued). "In clinical practice, human albumin is used in various intensive care unit indications to deal with a wide range of problems, from volume replacement in hypovolemic shock, or sepsis, to treatment of ascites in patients with liver cirrhosis." (PMID 26136776, 2015). "This led to the recently published ALBIOS trial of albumin supplementation in patients with sepsis, powered specifically to detect mortality difference in this more homogeneous group." (PMID 25276346, 2014). "Compared with saline, the use of albumin for resuscitation slightly improved outcome in severe sepsis patients (OR 0.81; 95% CI, 0.64 to 1.08; P = 0.09)." (PMID 25499187, 2014). "With the advantage of restoring effective volume and maintaining colloid osmotic pressure, albumin is considered to be administered in addition to crystalloid in the initial fluid management of patients with severe sepsis and septic shock." (PMID 25499187, 2014). "The results of the Albios trial of albumin supplementation for sepsis indicate that positive effects of albumin are limited to patients with shock." (PMID 25034180, 2014). "Studies were eligible if they compared the effects of albumin versus crystalloid therapy on mortality in adult patients with severe sepsis and septic shock." (PMID 25499187, 2014). "Further large randomized controlled trials are necessary to determine the potential benefits of albumin in patients with severe sepsis and septic shock." (PMID 25499187, 2014). "The impact of albumin on mortality in patients with severe sepsis compared with saline was estimated from two trials, the heterogeneity was determined to be non-significant (P = 0.99, I2 = 0%)." (PMID 25499187, 2014). "The recent surviving sepsis campaign guidelines advocate the use of albumin for volume expansion after the use of crystalloids." (PMID 25180196, 2014). "Three additional clinical trials are currently underway attempting to answer the question of potential albumin benefit in sepsis, one of which is specifically looking at patients with septic shock." (PMID 25625012, 2014). "Following the results of the SAFE study suggesting a benefit of albumin administration in patients with sepsis, several groups designed RCTs to further evaluate albumin use in this specific group of patients." (PMID 25042164, 2014). "The predefined subgroup analysis of the Saline versus Albumin Fluid Evaluation (SAFE) study suggested albumin potentially resulted in lower mortality in patients with severe sepsis." (PMID 25499187, 2014). "We found decreased serum albumin levels in the septic elderly patients compared to adult patients at both 1 and 30 days after sepsis (P <0.05 in elderly survivors, P <0.01 in elderly non survivors)." (PMID 24962182, 2014). "One thousand eight hundred patients with severe sepsis and septic shock were treated with either albumin and crystalloids, or crystalloids alone for 7 days (1:1 distribution)." (PMID 25625012, 2014). "As a result of few investigators emphasizing the use of albumin in patients with severe sepsis, let alone septic shock, a meta-analysis is needed to address the outcome of albumin as fluid therapy." (PMID 25499187, 2014). "We analyzed serum albumin levels at day 1 and day 30 after sepsis in the patients to address the impaired catabolism in the elderly patients." (PMID 24962182, 2014). "The effects of resuscitation with albumin on 90-day mortality in patients with severe sepsis was estimated from five trials, and the heterogeneity was also determined to be non-significant (P = 0.86, I2 = 0%)." (PMID 25499187, 2014). "A meta-analysis is imminent for stressing the role of albumin in resuscitating patients with severe sepsis and septic shock." (PMID 25499187, 2014). "In sepsis, infection, trauma, or major surgery, albumin level decreases by 1–1.5 g/dl over 3–7 days." (PMID 25074590, 2014). "In this meta-analysis, the effect of albumin as a resuscitation fluid on mortality in severe sepsis and septic shock was investigated." (PMID 25499187, 2014).
Sepsis (continued). "Until now, no researches have yet been designed to assess the dose-response relationship between albumin exposure and mortality rate in patients with sepsis." (PMID 25474401, 2014). "Guidet and colleagues assessed the cost-effectiveness of albumin as given in the SAFE study on patients with severe sepsis and septic shock admitted to one of 35 French ICUs." (PMID 25042164, 2014). "Although previous meta-analyses have explored the impact of albumin in resuscitating critically ill and sepsis patients, few investigators focused on the use of albumin in patients with severe sepsis, especially with septic shock." (PMID 25499187, 2014). "The results suggested a trend toward reduced 90-day mortality in severe sepsis patients resuscitated with albumin compared with crystalloid and saline." (PMID 25499187, 2014). "In this meta-analysis, a trend toward reduced 90-day mortality was observed in severe sepsis patients resuscitated with albumin compared with crystalloid and saline." (PMID 25499187, 2014). "In this preliminary study, we observed associations between baseline biomarkers E-Selectin and urine albumin-to-creatinine ratio (ACR) and the risk of future AKI after sepsis." (PMID 24826374, 2014). "The authors therefore concluded that albumin administration was a cost-effective intervention in patients with severe sepsis or septic shock." (PMID 25042164, 2014). "Compared with crystalloid, a trend toward reduced 90-day mortality was observed in severe sepsis patients resuscitated with albumin (odds ratio (OR) 0.88; 95% CI, 0.76 to 1.01; P = 0.08)." (PMID 25499187, 2014). "Firstly, it is vulnerable to bias because the most influential trial included was the pre-defined subgroup of patients with severe sepsis in the SAFE (the saline versus albumin fluid evaluation) study." (PMID 25474401, 2014). "In agreement with this, we observed that the severity of tubulointerstitial injury induced by albumin overload in a sepsis animal model is also correlated to the level of IL-10." (PMID 25302946, 2014). "Current data suggest that fluid resuscitation of albumin for severe sepsis and septic shock is recommended over hydroxyethyl starch, which can be used in the early phase of ALI/ARDS resuscitation without worsening EVLWI." (PMID 25520837, 2014). "Compared with saline, the use of albumin for resuscitation slightly improved the outcome in severe sepsis patients (OR 0.81; 95% CI, 0.64 to 1.03; P = 0.09); however, the results were not statistically significant." (PMID 25499187, 2014). "A trend toward reduced 90-day mortality was observed in severe sepsis patients resuscitated with albumin compared with crystalloid." (PMID 25499187, 2014). "In this meta-analysis, the results suggested a trend toward reduced 90-day mortality in severe sepsis patients resuscitated with albumin compared with crystalloid and saline." (PMID 25499187, 2014). "Hitherto, there are still many unsolved issues about albumin administration in patients with sepsis." (PMID 25474401, 2014). "This study did not consider several coexisting clinical factors that affect warfarin and albumin metabolism and renal function, including hypovolemia, sepsis, and medication concurrently prescribed with warfarin." (PMID 23560034, 2013). "Altogether, these results and ours suggest a possible benefit of albumin resuscitation in cirrhotic patients with severe sepsis, that remains to be prospectively investigated." (PMID 23601847, 2013). "In clinical practice serum albumin is often considered a marker of nutritional status and a negative phase protein that decrease in concentration during injury and sepsis." (PMID 23565300, 2013). "The main finding of our study is that markers of inflammation and of the severity of illness, specifically CRP and albumin levels at discharge, correlate with long-term prognosis (up to 90 days) after a sepsis episode." (PMID 23555017, 2013).
Sepsis (continued). "The second set of indications is linked to factors associated with high mortality: an elevated ASA score, an APACHE score > 15, severe sepsis (leukocytosis, albumin < 21 g/dL, hemoglobin < 9,5 g/L), pleural effusion, and a malignant PLA origin." (PMID 22536008, 2012). "Based on our own data, we specifically adhered to a minimal period of convalescence of 6 weeks, aimed to operate on patients with an albumin concentration >25 g/L, and treated sepsis more aggressively." (PMID 22669399, 2012). "The ROC curves constructed for the albumin level and the hemoglobin level (chosen as a sign of severity of the sepsis) showed that an albumin below 21 g/L predicted mortality with a sensitivity of 60% and a specificity of 80%." (PMID 22536008, 2012). "Severe leptospirosis and sepsis are also characterized by a concomitant decrease in plasma albumin concentration consequent to a functional liver injury or increased vascular permeability possibly caused by NEFA toxicity." (PMID 22529526, 2012). "Despite these limitations, we provide evidence that sepsis, in its early development, is associated with loss of the perm-selectivity of the GFB, as documented by leakage of albumin into urine." (PMID 22108136, 2011). "In its initial phase, sepsis is associated with a significant alteration in the composition of the GFB-associated glycocalyx, with loss of GFB perm-selectivity as documented by albumin leakage into urine." (PMID 22108136, 2011). "In our study, total cortisol-to-albumin ratio was very high during acute sepsis and presented the best on admission outcome predictor." (PMID 20615266, 2010). "Albumin levels decreased significantly in falciparum malaria (P<0.001), and moderately in sepsis (P<0.05) and left ventricular failure patients (P<0.05)." (PMID 20339175, 2010). "Albumin, a weak acid affects this balance in conditions like sepsis, where its levels decrease as it is lost into the extra-vascular compartment because of increased vascular permeability." (PMID 20859489, 2010). "An inverse correlation was demonstrated between MIF and delta max cortisol or the delta max cortisol/albumin ratio in patients with severe sepsis or septic shock." (PMID 20021698, 2009). "In trauma and sepsis, cardiac index and oxygenation were higher after administration of hydroxyethyl starch than hyperoncotic albumin." (PMID 18318896, 2008). "In five trials, the effects of hyperoncotic albumin were separately investigated among patients with either trauma or sepsis." (PMID 18318896, 2008). "Logistic regression revealed that among the seven candidate risk factors (admission plasma gelsolin, IL-6, IL-10, TNF-α, albumin, age and sex), admission plasma gelsolin was the only independent factor able to predict the occurrence of severe sepsis." (PMID 18706105, 2008). "In the subset of 1218 SAFE trial patients with severe sepsis, a trend toward reduced mortality was evident in the albumin group (odds ratio, 0.81; 95% confidence interval, 0.63–1.04; p = 0.09)." (PMID 18218122, 2008). "In light of these disparate survival trends, a need exists for an adequately powered outcome trial directly comparing HES and albumin in sepsis." (PMID 18218122, 2008). "In rodents with sepsis, colloidal iron dioxide, 14C-labelled amino acids and 125I-labelled albumin have been shown to pass from the circulation into the brain parenchyma in a similar manner to that seen in portosystemic encephalopathy." (PMID 15693962, 2005). "In the present study, patients who received albumin were also more severely ill, with a higher frequency of cancer, liver cirrhosis, and sepsis, and significantly higher SAPS II scores." (PMID 16356223, 2005). "Patients who received albumin were more likely to have cancer or liver cirrhosis, to be surgical admissions, and to have sepsis." (PMID 16356223, 2005). "We collected data on hematocrit, albumin levels, and sepsis status." (PMID 42078461, 2026).
Sepsis (continued). "Additionally, albumin, a key component of all three scores, often drops in sepsis and trauma due to increased capillary permeability, impaired liver function, and augmented inflammation." (PMID 40788397, 2025). "In contrast, a higher albumin level has been found to be inversely related to sepsis, suggesting that a lower albumin level may signal the presence of severe infection." (PMID 39975676, 2025). "Albumin, a pivotal plasma protein necessary for maintaining colloid osmotic pressure and transporting hormones and drugs, is extensively employed in fluid resuscitation for sepsis." (PMID 40841985, 2025). "The observed decrease in IAM likely reflects not only albumin redistribution due to capillary leak but may also be influenced by reduced hepatic albumin synthesis and increased degradation in the context of sepsis-induced catabolism." (PMID 40806877, 2025). "Yet, the volume sparing effect of albumin infusion in sepsis is limited and whether it leads to improved outcomes is still under debate." (PMID 40057738, 2025). "However, during sepsis, systemic inflammation disrupts these regulatory mechanisms, leading to significantly elevated transcapillary escape rates of albumin." (PMID 40806877, 2025). "According to the SHAP chart, PCT, PT, albumin and sex were closely related to sepsis." (PMID 39975676, 2025). "Future studies may investigate whether integrating IAM with serum albumin measurements enhances the clinical management of sepsis-related fluid imbalance and guides individualized resuscitation strategies." (PMID 40806877, 2025). "However, the exclusion of patients with conditions likely to impact albumin levels independently of acute sepsis, along with literature supporting its role as a marker of capillary leak, supports its use in this exploratory model." (PMID 40710030, 2025). "A meta-analysis has suggested that albumin may reduce 90-day mortality in patients with septic shock, and potentially improve survival in those with sepsis compared to crystalloids." (PMID 40649163, 2025). "Procalcitonin, CRP, and albumin, along with baseline investigations, were sent on the day of admission (day 0), day 2 of admission, and day 7 of admission for all the children with suspected sepsis." (PMID 40351994, 2025). "The aim of this study was to evaluate the utility of serum lactate, albumin, and BE levels—while controlling for factors that may influence these parameters—in predicting prognosis and mortality in patients diagnosed with sepsis." (PMID 40868186, 2025). "Our findings suggest a more intricate interaction between fibrinogen and albumin levels in sepsis." (PMID 40607037, 2025). "However, few studies have investigated the efficacy of albumin infusion in the complications of sepsis in patients with AP." (PMID 40773463, 2025). "From a clinical perspective, albumin presents an attractive treatment option, as it is already prescribed in the treatment of cardiovascular and renal complications from advanced liver disease, as well as sepsis." (PMID 40806286, 2025). "A large cohort study including patients with sepsis and cirrhosis (25% with septic shock) found that despite a higher mortality in patients who received albumin, after adjustment for time-dependent administration and baseline confounders, albumin was associated with reduced 28-day mortality." (PMID 40386509, 2025). "This nomogram, which includes variables such as sepsis, use of human albumin, mechanical ventilation, use of aminoglycosides, and Scr levels, can predict the occurrence of AKI in AHF patients upon their admission to the ICU, aligning with the current emphasis on personalized medicine." (PMID 40124680, 2025). "Additional predictors included advanced age, sepsis diagnosis, low serum albumin, and acute physiology and chronic health evaluation II ≥ 35; presentation during daytime hours was associated with reduced mortality (odds ratio, 0.54; 95% confidence interval, 0.30–0.97; P = .04)." (PMID 41431014, 2025).